DEFA1 (defensin alpha 1)
Diseases named in the same sentence as DEFA1 in open-access papers (continued):
Sharing a sentence is not in itself a finding about the gene and the disease.
systemic lupus erythematosus (2 papers, 2007 to 2009). An autoimmune multi-organ disease typically associated with vasculopathy and autoantibody production. "Increase in transcript abundance for genes included in this module may be an indication of an increase in the abundance of immature neutrophils (for example, DEFA1, DEFA3, FALL-39) as was reported earlier in patients with systemic lupus erythematosus." (PMID 19903332, 2009).
urinary tract infection (2 papers, 2018 to 2023). "Previous study reported that reduced copy numbers of the DEFA1 gene was associated with recurrent urinary tract infections in children." (PMID 36980071, 2023). "Reduced DEFA1/DEFA3 copy number has been associated with higher susceptibility to recurrent urinary tract infections (UTIs) in children with vesicoureteral reflux and HIV infection." (PMID 29950924, 2018).
acute myeloid leukemia (1 paper, 2022). Acute myeloid leukemia (AML) is a group of neoplasms arising from precursor cells committed to the myeloid cell-line differentiation. "The mRNA expression levels of DEFA1, DEFA3, and DEFA4 in tumor tissues were generally lower than those in normal tissues but significantly higher in tumor cells of acute myeloid leukemia than those in normal tissues." (PMID 36703795, 2022).
appendicitis (1 paper, 2016). Acute inflammation of the vermiform appendix. "The results confirm the microarray findings that appendicitis patients show significantly elevated circulating levels of mRNA for ALPL and IL8RB, while showing reduced levels of DEFA1 compared to patients with other abdominal conditions (ABD)." (PMID 27417541, 2016).
bladder cancer (1 paper, 2022). "The plasma levels of DEFA1-3 in patients with bladder cancer are parallel to the progression and pathological stage of malignant tumor, suggesting that DEFA1–3 can promote bladder cancer invasion and could be potential indicators of disease progression." (PMID 36703795, 2022).
Cirrhosis (1 paper, 2022). A chronic disorder of the liver in which liver tissue becomes scarred and is partially replaced by regenerative nodules and fibrotic tissue resulting in loss of liver function. "Regarding HCC risk, development of HCC showed inverse associations compared to persons with cirrhosis with two proteins, including DEFA-1 [ORC2v.C1 = 0.06 (95% CI: 0.02–0.20)] and ITGAM [ORC2v.C1 = 0.20 (95% CI: 0.08–0.40)]." (PMID 36358697, 2022). "However, the magnitude of association with late cirrhosis development was attenuated for DEFA-1 and ITGAM." (PMID 36358697, 2022). "In contrast to cirrhosis, DEFA-1 and ITGAM levels were inversely associated with HCC risk." (PMID 36358697, 2022). "We identified two individual proteins (DEFA-1, and ITGAM) that were positively associated, and two individual proteins (CCL11 and SCF) that were negatively associated with the development of cirrhosis." (PMID 36358697, 2022).
diabetes (1 paper, 2020). "To investigate the influence of medication and diabetes on PR3, ANX3, MMP9, and DEFA1 levels, we segregated our subjects based on either diabetes status or statin treatment." (PMID 31935243, 2020).
emphysema (1 paper, 2012). "Based on this latter finding, we examined whether ZZ AAT deficiency-related emphysema patients treated with Prolastin® had lower DEFA1 expression in their lungs." (PMID 22621770, 2012).
endometriosis (1 paper, 2017). The growth of functional endometrial tissue in anatomic sites outside the uterine body. "Of these eight loci, three were associated with all endometriosis (LAMC3, CAPN14 and DEFA1), and six with Stage B disease (NAALADL2, NR2C1, C14orf132, FOXP2, CDH20 and LAMC3)." (PMID 28333195, 2017).
esophagitis (1 paper, 2025). An acute or chronic inflammatory disease affecting the esophageal wall. "Microarray analysis in patients with esophagitis also demonstrated that a four-week administration of Lactobacillus rhamnosus GG regulated duodenal expression of Defa1." (PMID 40872558, 2025).
Graves ophthalmopathy (1 paper, 2024). An autoimmune disorder of the EYE, occurring in patients with Graves disease. "The alpha-defensins DEFA1, DEFA1B, and DEFA3 are overexpressed in orbital adipose tissue from patients with Grave’s ophthalmopathy." (PMID 38668354, 2024).
Hernia (1 paper, 2016). "Abdominal patients showed significantly elevated ALPL, IL8RB, and DEFA1 compared to patients with hernia (HER)." (PMID 27417541, 2016).
infertile (1 paper, 2023). "A reliable decrease in endometrial TGFβ1 and bFGF2 concentrations in combination with increased DEFa1 concentration was demonstrated in the infertile group relative to the fertile group." (PMID 37108732, 2023).
influenza (1 paper, 2021). An acute viral infection of the respiratory tract, occurring in isolated cases, in epidemics, or in pandemics; it is caused by serologically different strains of viruses (influenzaviruses) designated A, B, and C, has a 3-day incubation period, and usually lasts for 3 to 10 days. "In comparison, three patients had high activation of only a subset of influenza-connected genes PRTN3, LTF, PGLYRP1, DEFA1B, DEFA1, DEFA4, ELANE, and MPO." (PMID 34335605, 2021).
Intellectual disability (1 paper, 2019). "For example, increased levels of alpha defensins (encoded by DEFA1) have been reported in the CSF of patients with AD, whereas mutations in DEAF1 gene can cause severe intellectual disability and behavioral problems." (PMID 31477183, 2019).
leukemia (1 paper, 2020). A malignant (clonal) hematologic disorder, involving hematopoietic stem cells and characterized by the presence of primitive or atypical myeloid or lymphoid cells in the bone marrow and the blood. "Human platelets and megakaryocytes have recently been reported to express defensin α-1 (DEFA1), also known as human neutrophil peptide-1 (HNP1), which co-localizes with platelet α-granules and has also been found in the cytoplasm of a megakaryoblastic leukemia cell line." (PMID 33042161, 2020).
liver disease (1 paper, 2022). "Consequently, DEFA-1 may have a bi-directional effect in the progression of liver disease in the context of chronic HCV infection." (PMID 36358697, 2022).
meningitis (1 paper, 2023). A disorder characterized by acute inflammation of the meninges of the brain and/or spinal cord. "Here, the levels of ALOX5, S100B, DEFA1, and GFAP in the CSF of patients with meningitis caused by different infectious agents were compared to those of healthy controls." (PMID 38115295, 2023). "A heat map was created to visualize the concentrations of DEFA1, GFAP, ALOX5, and S100B in the meningitis and healthy control groups." (PMID 38115295, 2023). "According to the heat map, ALOX5, S100B, DEFA1, and GFAP levels were partially increased in the meningitis group versus controls." (PMID 38115295, 2023). "ROC curve analysis was performed to differentiate the variation in ALOX5, S100B, DEFA1, and GFAP between groups to distinguish meningitis patients from healthy individuals and from different types of meningitis." (PMID 38115295, 2023). "Comparison of CSF levels of ALOX5, S100B, DEFA1, GFAP in the groups with infectious meningitis and in the healthy control groups." (PMID 38115295, 2023). "DEFA1, GFAP, ALOX5, and S100B successfully distinguished patients with meningitis from controls." (PMID 38115295, 2023). "This study showed that the parameters ALOX5, S100B, DEFA1, and GFAP could discriminate between meningitis patients and healthy controls, although with varying degrees of reliability." (PMID 38115295, 2023).
pancreatic cancer (1 paper, 2025). "As an initial validation, we tested the direct effect of recombinant human DEFA1/3 on the viability of several pancreatic cancer cell lines." (PMID 41303383, 2025). "Defensin-enriched platelet-like particles (defensin-rich platelets, DRPs) and recombinant DEFA1/3 enhanced pancreatic cancer cell proliferation, migration, and three-dimensional growth in vitro and promoted tumor dissemination in zebrafish xenografts." (PMID 41303383, 2025).
rhabdomyosarcoma (1 paper, 2025). A rare aggressive malignant mesenchymal neoplasm arising from skeletal muscle. "At the same time, downregulation of innate immune effectors, including neutrophil defensins (DEFA1/3), and fibrinogen-like protein 1 (FGL1), along with various immunoglobulin chains, might be the cause of impaired antigen presentation and immune surveillance in rhabdomyosarcoma." (PMID 40710368, 2025).
vitiligo (1 paper, 2025). Generalized well circumscribed patches of leukoderma that are generally distributed over symmetric body locations and is due to autoimmune destruction of melanocytes. "We identified seven proteins (HEPHL1, PRDX1, DEFA1, CSGALNACT2, HERC4, NDC80, and SPHK2) causally associated with vitiligo risk." (PMID 40856249, 2025).
Warthin’s tumour (1 paper, 2012). "A similar expression pattern of DEFA-1/3 and -4 in cystadenolymphomas and inflamed salivary glands underlines a potential importance of immunological reactions during the formation of Warthin’s tumour." (PMID 23050799, 2012).
infection (15 papers, 2006 to 2025). The state of being infected such as from the introduction of a foreign agent such as serum, vaccine, antigenic substance or organism. "Previous studies found that decreased levels of DEFA1 were associated with several infectious diseases, while increased levels of DEFA1 may protect against the progression of infection." (PMID 36980071, 2023). "However, 5-LO deficiency compromised the expression of Defa1 induced by infection." (PMID 29247243, 2017). "Relatively large fold-change increases (~20-fold) were identified in RNAs coding for neutrophil primary granule markers, especially neutrophil α-defensins (DEFA1) in infections such as pneumonia." (PMID 41385588, 2025). "Blood samples were drawn in RNA preservative (Tempus) and whole blood RNA was analyzed by droplet digital PCR (ddPCR) for RNA transcripts related to neutrophil response to infection by bacterial (DEFA1; ALPL, IL8RB/CXCR2), and viral (IFI27, RSAD2) pathogens." (PMID 41385588, 2025). "We observed a significant reduction in the gene expression of α-defensin-1 (Defa1) in the lungs of Il22−/− mice after 14 days of infection." (PMID 32517114, 2020). "In saline-pretreated mice, SL1344 infection resulted in a significant induction of Reg3γ (3.8-fold), Defa1 (6-fold), MMP-7 (2.6-fold), and Ang-4 (8.6-fold) expression." (PMID 29616040, 2018). "Infection of paraoxon-pretreated mice also led to a significant enhancement in the expression of Defa1 (2.3-fold), MMP-7 (1.6-fold), and Ang-4 (4.3-fold) antimicrobial proteins, but not Reg3γ which was already upregulated by paraoxon treatment." (PMID 29616040, 2018). "Our findings indicate that following oral infection with Salmonella, saline-pretreated mice strongly upregulated the expression of RegIIIγ, Defa1, MMP-7, and Ang-4." (PMID 29616040, 2018). "Of interest, LTB4 administration to Alox5−/− mice restored the expression of Defa1, and at the 3rd day post-infection, BALF of infected and LTB4 treated Alox5−/− mice exhibits comparable levels of α-defensin-1 to that of 129sv mice." (PMID 29247243, 2017). "It was proposed that a lower DEFA1 protein level may contribute to impaired innate defenses and a weaker functioning of antimicrobial activity, and consequently leads to infections." (PMID 36980071, 2023). "In addition, DEFA1/DEFA3 CNV has been associated with inflammation, infection, and several autoimmune diseases." (PMID 29950924, 2018). "Notably, we detected that pre-treatment of AMJ2-C11 cells with LTB4 increased the expression of Defa1 at 2 and 6 h post-infection with A. xylosoxidans." (PMID 29247243, 2017). "Effectively, it has been demonstrated that DEFA1 could protect against infection with some enveloped virus (i.e., CMV, HSV, influenza virus)." (PMID 24695528, 2014). "Selection of DEFA1 was made on the basis of its high fold-change, the possible functional association of this protein with WNV pathobiology or the potential use as severe infection biomarker, and the availability of the required ELISA kits." (PMID 24695528, 2014). "Omental adipocytes could play a major role in protecting against infection by generating defensin (DEFA1-3)." (PMID 21647223, 2011). "This could be the case of DEFA1A3 in which variation in DEFA1 and DEFA3 copy number, and DEFA3 absence could underlie variable resistance to infection among individuals." (PMID 17214878, 2007). "In addition, the polymorphisms were not important predictors of susceptibility to infection, suggesting that they do not influence DEFA1/DEFA3-mediated or DEFB1-mediated responses to infection." (PMID 16700921, 2006). "Of note, raised DEFA1 and MPO levels characterized symptomatic infections while elevated levels of calprotectin marked SARS-CoV-2 infections irrespective of clinical presentation." (PMID 34746027, 2021). "Similar to DEFA1, MPO levels were unaltered during subclinical infection (p=0.85) while a significant increase was observed in the patients with mild (p=0.01) and severe (p=0.02) disease." (PMID 34746027, 2021).
infection (continued). "We observed that at the 1st day post-infection, treatment with LTB4 rescued the expression of Defa1 in lungs of infected Alox5−/− mice." (PMID 29247243, 2017). "DEFA1 and DEFA4 have been selected to identify the network of genes regulating their expression considering α-defensins as potential novel targets of C. parvum to persist the infection." (PMID 34946170, 2021). "Lower DEFA1/DEFA3 CNV may lead to impaired innate defenses and subdued inflammatory signals, which may ultimately be permissive to infections." (PMID 29950924, 2018). "Expression of mucin 5 AC (Muc5AC), a pivotal player for worm expulsion, or defensin alpha 1 (Defa1) was not affected by the infection at this time." (PMID 26377648, 2015). "Thus, higher expression of DEFA1 during severe COVID-19 infection was independent of mechanical ventilation or secondary infection." (PMID 34746027, 2021). "The rise in DEFA1 levels was independent of secondary infections." (PMID 34746027, 2021). "However, Defa1 expression in WT mice was similar to that of non-infected animals after 14 days of infection, suggesting that this AMP does not play a significant role during H. capsulatum infection." (PMID 32517114, 2020).
tumor (9 papers, 2010 to 2025). "In comparison with healthy tissue (set 1 as baseline), the gene expression of DEFA-1/3 and -4 was significantly (p<0.05) increased in all tumours." (PMID 23050799, 2012). "Notably, DRPs had an even greater effect on tumor cell viability, suggesting that DEFA1/3 enrichment enhances the pro-tumorigenic potential of platelet-derived particles." (PMID 41303383, 2025). "Moreover, our in vivo zebrafish xenograft assays confirmed that DEFA1/3-enriched platelets promote tumor growth and dissemination in a complex biological environment." (PMID 41303383, 2025). "Thus, HRG expression by MZL tumor cells is accompanied by changes in gene expression, including DEFA1, characteristic of an antitumoral response." (PMID 35847718, 2020). "In contrast, Paneth cell markers, including defensin alpha 1 (DEFA1), lysozyme (LYZ), and SOX9, were upregulated in tumor tissue." (PMID 41303610, 2025). "Platelet-derived DEFA1/3 acts as a functional modulator of PDAC progression, linking platelet granule content to tumor aggressiveness and highlighting a potential biomarker and therapeutic target within the platelet–tumor axis." (PMID 41303383, 2025). "Three genes, DEFA1, DEFA3 and LOC728358, map to a refined region in 8p23.1 (8:6789275-6889920) and the ANGPT2 gene maps an adjacent region (8:6342789-6444367) and all show decreases expression in the tumor samples." (PMID 20799942, 2010). "Interestingly, Paneth cells are producers of antimicrobial peptides that interact with the gut microbiota and modulate immune cells, showing a contrasting pattern, being increased in tumor tissue, as indicated by the upregulation of the genes LYZ, DEFA1, SOX9, and WISP1." (PMID 41303610, 2025). "Importantly, platelets and mks have been shown to express Defensin Alpha 1/3 (DEFA1/3) transcripts and proteins, which localize to α-granules and are released upon activation, suggesting a previously underappreciated immunomodulatory role of platelet-derived α-defensins in the tumor milieu." (PMID 41303383, 2025).
cancer (4 papers, 2020 to 2025). A tumor composed of atypical neoplastic, often pleomorphic cells that invade other tissues. "Lower concentrations of DEFA1-3, however, may promote cancer cell motility and invasion, highlighting the importance of concentration in defining function." (PMID 41009818, 2025). "The defensin family genes (DEFA1, DEFA1B, DEFA3) and CD177, typically linked to neutrophil function, may indicate the involvement of innate immunity in cancer development." (PMID 40227838, 2025). "Still, DEFA1 cannot be removed, because it plays a key role in separating the CTRL group from malignant tumors." (PMID 32731530, 2020).
DEFA1 also shares sentences with these, for which no sentence is quoted: Bacterial Infections (2 papers); gastric cancer (2); infectious disease (2); acute respiratory distress syndrome (1); adenocarcinoma (1); aneurysm (1); atherosclerosis (1); autoimmune disease (1); autonomic neuropathy (1); bilirubin encephalopathy (1); colon cancer (1); colonic adenocarcinoma (1); colonic mucinous adenocarcinoma (1); cystic fibrosis (1); endothelial dysfunction (1); idiopathic thrombocytopenic purpura (1); Kawasaki disease (1); leptospirosis (1); mucoepidermoid carcinoma (1); Nephropathy (1); parasite infection (1); peripheral neuropathy (1); psychotic disorder (1); pulmonary TB (1); retinopathy (1); schizophrenia (1); vasculitis (1); vesicoureteral reflux (1).